C5 (complement C5)
Diseases named in the same sentence as C5 in open-access papers (continued):
Sharing a sentence is not in itself a finding about the gene and the disease.
infection (continued). "Although the normal physiological role of C5 in the context of response to infection has been well established, our results suggest a novel role for C5 in normal cardiac signaling." (PMID 21829669, 2011). "After infection, macrophages were washed then challenged with sheep red blood cells (RBC) pre-opsonized with either rabbit IgG or IgM and C5-deficient serum, to direct RBC for phagocytosis through FcγR and CR3 respectively." (PMID 18201246, 2008). "However, the amount of C5-positive VECs was significantly reduced upon infection with the VVC strain (17.9%), as compared to uninfected or Colonizing strain-infected VECs." (PMID 40985395, 2025). "However, a thorough investigation of the underlying mechanism and potential compensatory pathways is warranted as well as the effect of C1q loss or inhibition as it appears to play a larger role in these infection than C3 and C5." (PMID 38881889, 2024). "Complement C5 contributes to activation of neutrophils and leukocytes involved in inflammatory response and C5a, an anaphylatoxin produced when complement is activated, is a chemoattractant that recruits immune cells to the site of infection or injury." (PMID 39109890, 2024). "The complement system is the first line of the innate immune system, which detects virus-infected cells at early stages and lyses them to prevent further infection, and coagulation factors can boost the complement system through the cleavage of C3 and C5, resulting in activation." (PMID 33271804, 2020). "In order to assess the respective roles of phagocytosis and MAC-mediated killing in clearance of M. catarrhalis, we employed a whole blood infection model, using human blood pre-treated with complement C5 inhibitor OmCI, phagocytosis inhibitor cytochalasin D or both." (PMID 32983170, 2020). "However, only A/J C5+/+ mice presented lung recovery on the sixth day of infection when compared with A/J C5−/−, C57BL/6 C5+/+, and C57BL/6 C5−/−." (PMID 31687410, 2019). "Ironically, many of the properties of complement C5 that aid in fighting infection within otherwise healthy individuals might be expected to increase metastasis in individuals with tumors." (PMID 27105526, 2016). "In comparing the groups with and without infection, the SNPs most significantly associated with infection were located in complement genes, including C3, C5, C6, C7, C9 and MBL2 (P < 10−6)." (PMID 27063552, 2016). "All remaining mice showed signs of illness 20 h after infection and were randomly assigned to the four treatment groups: 16 mice to the placebo group, 15 mice to the dexamethasone group, 31 mice to the anti-C5 antibody group, and 30 mice to the dexamethasone plus anti-C5 antibody group." (PMID 26272468, 2015). "The C4a and C5 viruses isolated in Vietnam and Taiwan have similar antigenic profiles and could be neutralized by the post-infection children sera." (PMID 23922846, 2013). "Like C3, C5 loss did not impact bacterial abundance, with similar numbers of bacteria on catheters and in the surrounding brain tissue of both wild type and C5 KO animals over the course of infection." (PMID 38881889, 2024). "Thus, BTH in eculizumab is associated with lack of inhibition of C5 (insufficient dose) or cases of strong complement activation (pregnancy, infection, etc.)." (PMID 39734592, 2024). "Furthermore, during the infection, the presence of C5 and its receptor C5aR1 may represent a double-edged sword." (PMID 31687410, 2019). "Besides contributing to control systemic or local infection, the inflammatory properties observed during C5 activation and the participation of receptors such as C5aR1 may be responsible for local tissue damage." (PMID 29568732, 2018). "Consistently, epithelial, stromal, and CD45+ immune cells in the intestine did not express appreciable levels of C5–C9 transcripts, and C5 protein remains undetectable in the gut lumen, even during infection, while C3 is robustly upregulated and secreted." (PMID 41031883, 2025).
infection (continued). "Eculizumab and ravulizumab do not prevent C5 from adopting a C5b-like conformation under conditions of high complement activation, such as major surgery, the third trimester of pregnancy and infection, in PNH red cells that are densely coated with C3b." (PMID 38541105, 2024). "Without smoothing, GO terms related to digestion as well as infection and autoimmune-related pathways and complement cascade components (C3, C5) were identified." (PMID 35380614, 2022). "In contrast, the concentration of C5a in the mock infection group was not statistically different (P > 0.05) to that of the C5 control group, congruent with Western blot results." (PMID 35087765, 2021). "In addition, the expression of c1ql2, C3, C5, C7, C9, CFB, and complement factor H (CFH) was regulated in rainbow trout stimulated with β-glucan upon infection with A. salmonicida, suggesting improved immune enhancement." (PMID 34835165, 2021). "In addition, we classified the patients into subgroups based on the infection with DENV-1 or DENV-2 and compared the levels of C2, C4b, C5, C5a, C9, factor D and factor I between these classified groups." (PMID 32913345, 2020). "On the other hand, other effector immune mechanisms probably compensate Complement impairment since the mice survival was not affected by the absence of C5 and its activated fragments, at least in the early stage of this infection." (PMID 29568732, 2018). "Formation of MAC occurs between 4 and 5 h (although C5 expression is not significantly up-regulated by infection until 8 h, a non-significant increase can be observed at 4 h)." (PMID 25496447, 2014). "Unlike infection in our C5aR1-/- mice, N. brasiliensis resistance described in FVB/N hosts could not be definitively attributed to deletion of C5, as this mouse strain possessed numerous other gene mutations." (PMID 39628481, 2024). "However, C5 is not essential, since a C5 null mutant virus can still accumulate and establish a systemic infection." (PMID 37676365, 2022). "Moreover, C3, C5, C2, C1S, C4BPA (genes involved in the complement pathway) and SERPING1 (a regulator of complement activation) were significantly up-regulated, indicating an important role of the complement pathway in this infection." (PMID 34203742, 2021). "Eculizumab is an anti-C5 antibody, but C5a receptor antagonists target C5a alone and do not inhibit MAC, so those antagonists may lessen risk of an infection with a pathogen such as Neisseria meningitidis seen with eculizumab." (PMID 29259684, 2016). "A subset of infections was additionally performed with mice lacking C5 or C5a receptors." (PMID 23189195, 2012). "While A/J C5+/+ and A/J C5−/− infected with LPF showed similar liver injury scores, C57BL/6 C5+/+ mice showed more liver injury than C57BL/6 C5−/− mice, suggesting the lack of C5 as a protective factor during LPF infection in C57BL/6 genetic background." (PMID 31687410, 2019).
tumor (79 papers, 2011 to 2026). "Clinically, C3 and C5 inhibitors have been explored for their potential to improve immune checkpoint blockade efficacy and limit tumor-associated inflammation." (PMID 40283026, 2025). "The study showed that Inc-TALC is packaged into exosomes and delivered to tumor-associated macrophages (TAMs), driving M2 polarization of microglia in a manner correlated with C5/C5a secretion." (PMID 41300283, 2025). "We used multi-omics approaches to evaluate the association of complement signature C3/C5/C3AR1/C5AR1 with tumor immune phenotypes and prognosis across various cancer types." (PMID 34439277, 2021). "It has been reported that C5‐encoded PR proteolytic product C5 promotes tumor cell invasion, suggesting that up‐regulation of this gene in tumors promotes tumor progression." (PMID 33934516, 2021). "More importantly, C5 and especially C5ar1 deficiency almost completely prevented tumorigenesis, as determined by the quantification of tumor numbers and size." (PMID 32754267, 2020). "In AOM/DSS-induced CRC mice, we found that the reduction in MDSCs and concomitant increase in CD8+ T cells in the tumor, blood and/or spleen correlated with the preventive effects of C5 and C5ar1 deficiency, and a C5aR1 antagonist on CRC development." (PMID 32754267, 2020). "CFB, C3, and C5 are commonly associated with changes in the tumor microenvironment." (PMID 37628784, 2023). "The result may also explain the observation that tumor burden in C5-deficient mice is greater than in C5ar1-deficient mice." (PMID 32754267, 2020). "Our findings are consistent with recent reports showing that C5 can be cleaved intracellularly in multiple cell types to promote C5a-C5aR1 signalling and tumour progression." (PMID 40695778, 2025). "Higher abundance of complement proteins C3 and C5 is linked to increased CRC risk and poorer prognosis, and have been implicated in treatment resistance and tumor progression." (PMID 41179292, 2025). "Ligand-receptor analysis between macrophages and tumor cells identify C5/C5AR1,SPP1/ITGA4, and TF/TFRC as the ligand-receptor signaling mechanism driving these niche-DE genes." (PMID 38217002, 2024). "To explore the role of C5 in tumor treatment, we analyzed publicly available scRNA-seq dataset from CRC patients treated with or without preoperative chemotherapy (PC) (GSE178318) and CRC patients before and after chemotherapy (GSE232525)." (PMID 38408082, 2024). "We found that the number of dendritic cells was significantly higher in tumor tissues than in brain metastases, and we also found that macrophage C5 was also significantly higher than in brain metastases." (PMID 37715019, 2023). "This allowed the identification of several highly specific VL-sdAbs, including C5, which specifically target cNHL cells in vitro and present promising in vivo tumor uptake." (PMID 36964198, 2023). "At first, the cleavage product of C3 followed by a series of reactions finally cleaves C5 into C5a which can promote tumor development by recruiting myeloid-derived suppressor cells (MDSCs)." (PMID 36769748, 2023). "Both results showed that PPIP5K2-regulated complement C5 recruited MDSC to remodel the tumor microenvironment." (PMID 35813475, 2022). "More importantly, we showed that both C5aR inhibitor CCX168 and complement C5 antibody inhibited metastasis and extended tumor-loaded mice survival by inhibiting MDSC infiltration in TME." (PMID 35813475, 2022). "Overall, our differential expression analysis suggests tumor context and stage-dependent heterogeneity in the expression of complement components C3, C5, C3AR1, and C5AR1 in different cancer types." (PMID 34439277, 2021). "Previous studies in cell lines found that c5 modulates tumor inflammation in CRC and has a pro-metastatic effect, while inhibition of the c5a receptor signaling severely impairs tumor metastasis." (PMID 34834411, 2021).
tumor (continued). "As the description above, not limited to C3, a series of complement related proteins, such as Serpind1, Cfd, C5, C1qbp, etc., were upregulated in tumor with YB1 treatment." (PMID 34489962, 2021). "C3, C3AR1, and C5 participate in the genesis and development of multiple tumor types, while their effects on ccRCC remain obscure." (PMID 34688260, 2021). "Our results suggest that C3, C5, C3AR1, and C5AR1 are associated with tumor immune evasion via dysfunctional T-cell phenotypes with a lesser contribution of T-cell exclusion." (PMID 34439277, 2021). "Further analysis revealed that C3, C5, C3AR1, and C5AR1 were associated with tumor immune evasion via dysfunctional T-cell phenotypes with a lesser contribution of T-cell exclusion." (PMID 34439277, 2021). "In 1996, in thyroid carcinoma the presence of IgG, together with C4d, C3d and C5-positive staining suggested tumor-specific classical pathway activation." (PMID 33113844, 2020). "In consistent, the counterpart tissues of C5- and C5ar1-deficient mice were infiltrated with significantly greater numbers of CD8+ T cells compared with the tumor tissues of WT and C3-deficient mice." (PMID 32754267, 2020). "In REACTOME pathway analysis, the most highly correlated pathway was activation of the C3 and C5 complement system in the tumor, which has a role in the regulation of the cancer microenvironment and has been suggested as a target in cancer immunotherapy." (PMID 31652813, 2019). "C5, one of the complements, was suggested to promote tumor progression controlling the tumor microenvironment." (PMID 30736371, 2019). "In previous studies complement C5 affected tumor progression at the level of the primary tumor, by increasing invasiveness or angiogenesis." (PMID 27105526, 2016). "Our results suggest that high local production of complement component 5 (C5) and janus kinase 1 (JAK1) at tumour site associates with better survival of ESFT patients, whereas locally produced interleukin 8 (IL8) is detrimental." (PMID 22084725, 2011). "Notably, Nb C5 specifically accumulated in tumor tissues at 24 h post‐injection, with partial signal detected in the liver, kidney, and lung." (PMID 40135833, 2025). "Functional assays in BLCA cell lines or organoid models, including C3 or C5 inhibition, could further reveal how complement activation impacts tumor progression, immune infiltration, and immunotherapy response." (PMID 40283026, 2025). "C5 could play a dual role: promoting immune suppression through C5a-mediated recruitment of MDSCs and enabling tumor cell lysis through MAC formation." (PMID 40309765, 2025). "To directly assess whether radiation could impact tumor cell–intrinsic expression of C5aR1 or C5, we turned to an in vitro system." (PMID 37824211, 2023). "Additionally, due to limited samples, no positive correlation was observed between the number of intratumoral C5/C5a+ cells and tumor size, which should be further studied in a larger cohort." (PMID 37064877, 2023). "Furthermore, this combination therapy also increased the MAC formation on dying tumor cell surfaces, as demonstrated by C5 staining." (PMID 35167491, 2022). "In addition, tumor inflammatory microenvironments were found to contain the complement-activating components C3, C4, C5, C1q, and MAC in many cancer models." (PMID 31236404, 2019). "Complement C5a also increased the invasiveness of tumor cells grown in the absence of immune cells, and tumors were less invasive in animals that did not encode complement C5." (PMID 27105526, 2016). "Furthermore, It has been found in number of cancer models that tumor inflammatory microenvironment constitutes complement activated fragments C3, C4, and C5, Clq, and MAC, high levels of IL-6 and TGF-β." (PMID 26198107, 2015).
tumor (continued). "On the basis that I-TAC, C5/C5a, IL-6, CD54, and IL-27 are the cytokines related to the immune system, we conclude that the KUP system acts as ROS photogenerators and induces the immune activity to control the release of cytokines, which cause the tumor eradication." (PMID 36932086, 2023). "In addition, M2 macrophages synthesize C1q, a complement component that binds to the Fc portion of anti-tumor antibodies and triggers the classical component cascade in the presence of complement components such as C1r, C1s, C4, C2, C3 and C5 produced by tumor cells." (PMID 37622111, 2023). "Several mechanisms could be responsible, including increased proteolytic activation of complement C5 in males, increased post-translational stability of complement C5 in males, or higher transcription of complement C5 in males from a tissue other than tumor or liver." (PMID 27105526, 2016). "In contrast, tumor tissues from C5- and C5aR1-deficient mice had increased infiltration of CD8+ T cells compared to wild-type and C3-deficient mice, suggesting that MDSCs may contribute to CD8+ T cell suppression and create an immunosuppressive tumor microenvironment." (PMID 41300283, 2025). "Mechanistically, MTX–TMPs recruited neutrophils to tumor sites through the UDP-glucose (UDPG) and complement component 5 (C5) pathways, thereby eliciting antitumor immunity." (PMID 40429976, 2025). "Several of these EPINs have promoters of differentially expressed genes (such as DLL1, STOM and SEC11C in the GEPIA tumor/normal dataset; ID2, RPS27, SEC11C, CASZ1, CRTC2, C5 and STOM in the LNCaP/LHSAR dataset; see Methods, Differential Gene Expression)." (PMID 38057321, 2023). "Linear regressions were performed to evaluate the ability of tumor burden (as % of body mass) to predict MYH10, TGBI, CTGF, and C5 relative abundance values." (PMID 35422813, 2022). "LncRNA-LncOVM maintains the stability of PPIP5K2 by inhibiting ubiquitination degradation and promoting the secretion of complement C5, thus allowing complement C5 to attract MDSC infiltration in the tumor microenvironment and promote tumor metastasis." (PMID 36601121, 2022). "Although accumulating evidence agrees on the pro-tumoral role of C5, C3, C3AR1, and C5AR1, the immune infiltration is largely controlled by the properties of the tumor cells themselves." (PMID 34439277, 2021). "In general, the expression of P3H2, COL10A1, and C5 in tumor tissues was significantly increased than that in normal tissues, and the expression of UHRF1, considered as a tumor suppressor gene, was higher in normal tissues than in tumor tissues." (PMID 33934516, 2021). "It has been demonstrated previously that complement components such as C1q, C3, C3a, C4, C5 and the MAC were deposited in the inflammatory tumor microenvironment." (PMID 24205138, 2013). "C5 and its receptor C5aR1 expression was verified at protein level by immunohistochemistry on an independent ESFT tumour tissue microarray." (PMID 22084725, 2011). "In addition, acute phase proteins (ORM1, CRP, SAA1) and complement cascade components (SERPINA1, C5, FGA) showed an obviously significant correlation with tumor size, reflecting a positive connection between inflammatory response and tumor size." (PMID 37460463, 2023). "C5 cleavage and activation in the tumor can also be accomplished through non-canonical complement pathways, that do not require the engagement of the entire complement cascade." (PMID 35860237, 2022). "The result showed that the lower mRNA expressions of C3, C5, CFB, and CLU were correlated with more advanced cancer stage, while the lower mRNA expressions of C1S, C8B, CFI, MBL2, and C4BPA were correlated with higher tumor grade in HCC patients." (PMID 34813686, 2022). "The C3 upregulation was further validated in paired tumor and adjacent normal tissues (P = 0.002); however, the C5 expression was not significantly different between paired samples (P = 0.546)." (PMID 31928530, 2020).